CLDN1 (claudin 1)
Diseases named in the same sentence as CLDN1 in open-access papers (continued):
Sharing a sentence is not in itself a finding about the gene and the disease.
tumor (continued). "Claudin-1 has also been shown to facilitate the collective migration of cancer cells in several tumor types." (PMID 34354941, 2021). "In gastric NENs tumor tissues, the epithelial markers Claudin-1, Zo-1 and E-cadherin were down-regulated, while the mesenchymal markers Vimentin and β-catenin were up-regulated as compared to non-tumorous tissues (p < 0.05)." (PMID 34037532, 2021). "The expression of claudin-1 decreases as the histopathologic grades progress and in the presence of tumor deposits." (PMID 34214117, 2021). "This indicates that the role of CLDN1 in tumor metastasis and in the enhanced presence of CIC markers CD44 and CD133 is not due to EMT pathway induction." (PMID 33828978, 2021). "In CRC, increased claudin-1 expression results in epithelial-to-mesenchymal transition and metastasis, while claudin-7 functions as a tumor suppressor." (PMID 34571860, 2021). "Results showed that bufalin treatment markedly decreased the protein levels of Ki-67, and increased the expression of Claudin-1 in tumor tissues, suggesting that bufalin inhibited tumor proliferation and impede EMT signaling pathway in HCC xenografts." (PMID 33990545, 2021). "The present findings showed that mRNA expression of CLDN-1 was positively correlated to larger tumor size in our population of BrCa." (PMID 33407452, 2021). "The expression of E-cadherin and claudin-1 is lower in the presence of tumor deposits (p = 0.004 and 0.007, respectively)." (PMID 34214117, 2021). "The aim of this study was to evaluate the functional significance of CLDN1 expression by using data from matched primary-recurrent OC tumor samples along with in vitro and in vivo studies." (PMID 33828978, 2021). "Among them, EMT, characterized by the downregulation of epithelial cell markers (E-cadherin and claudin-1) and upregulation of mesenchymal cell markers (N-cadherin and vimentin), is an early event in tumor metastasis." (PMID 32477134, 2020). "In mouse xenograft studies, tumor growth and metastasis is regulated by genetic modulation of CLDN-1." (PMID 31952355, 2020). "Based on the literature, CLDN-1 is one of the most deregulated claudins in human cancer and can function as a tumor promoter or suppressor depending on the type of cancer." (PMID 31952355, 2020). "CLDN-1 acts alone or in combination with other molecules to exert its tumor promoting or suppressing effect." (PMID 31952355, 2020). "CLDN1 and 2 expression correlates with tumor grade, and CLDN1, 3, and 4 expression is considered a poor prognostic factor." (PMID 33172177, 2020). "It has been shown previously that CLDN-1 induces the generation of tumor lymphatic vessels and increases the lymph node metastasis." (PMID 31952355, 2020). "The role of CLDN-1 as a tumor promoter is mostly through its effect on the invasion or motility of cancer cells." (PMID 31952355, 2020). "The expression levels of AXL, GAS6, Claudin-1, and Cofilin-1 genes were investigated in a fresh, frozen tumor sample and normal adjacent tissue by real-time PCR (RT-PCR)." (PMID 31700829, 2019). "We suggest that CLDN1 or CLDN11 overexpression impaired tumor sensitivity to anticancer drugs mediated by interference with penetration of the drugs into inner areas of the spheroid." (PMID 31551535, 2019). "CLDN1 can promote or suppress tumor proliferation in different cancers or even in different histological subtypes of the same cancer." (PMID 30910845, 2019). "Claudin-1 and occludin modulate intestinal-mucosal structure and function, and integrate diverse processes, such as gene transcription, tumor suppression, cell proliferation, and cell polarity." (PMID 30360365, 2018). "In the miRNA-mRNA negative regulatory networks, miR-204-5p regulated the largest number of target genes, such as TNFRSF12A. miR-146b, miR-204, miR-7-2, and FN1 were associated with tumor stage in PTC, and TNFRSF12A and CLDN1 were related to prognosis." (PMID 30414611, 2018).
tumor (continued). "MMP8, ITGB2, and CLDN1 are well-studied proteins that have evolved with tumor cell’s higher ability for invasion." (PMID 29520031, 2018). "Especially claudin-1 and occludin integrate diverse processes, such as gene transcription, tumor suppression, and cell proliferation." (PMID 30360365, 2018). "Claudin-1 is one of the most dysregulated claudins in human cancers and functions as a cancer promoter and tumor suppressor depending on cancer type." (PMID 30060617, 2018). "Previous studies including our report revealed that several molecules, such as E-cadherin, Δ-catenin, ZO-1, ZO-2, and claudin-1 affected tumor progression, according to the change in their own intracellular localization." (PMID 30042826, 2018). "Western blot analysis of subcellular protein extracts from three of the primary tumor samples with moderate or strong CLDN1 expression showed that CLDN1 expression was mainly localized at the membrane." (PMID 28659146, 2017). "Further more, the WB results proved that the Claudin 1, Claudin 4, and Claudin 7 proteins were closely related to the mechanism of tumour growth and metastasis." (PMID 28376864, 2017). "While somewhat contradictory to claudin-1 as a tumor suppressor, recent studies suggest that higher expression levels of claudin-1 induce EMT in human liver cells through the activation of the ERK signaling pathway." (PMID 28038455, 2017). "When E-cadherin was overexpressed in PC3-TxR and DU145-TxR cells, the expression of Vimentin and Claudin-1 was down-regulated, and tumor cell migration and invasion were inhibited." (PMID 28356132, 2017). "The inhibitory effect of the 6F6 mAb on tumor growth was confirmed in mice xenografted with DiFi CRC cells (wild type KRAS) that overexpress CLDN1 (p = 0.03)." (PMID 28659146, 2017). "Claudin 1, Claudin 4, and Claudin 7 were the main proteins contributing to the oridonin anti-tumour effect based on the inhibition of angiogenesis." (PMID 28376864, 2017). "CLDN1 has been predicted to act as a tumor suppressor gene in carcinomas of breast, prostate, colon, and liver." (PMID 28055967, 2017). "Gene expression profiling and immunochemistry analysis of normal and tumor tissue samples from patients with stage IV CRC were used to determine CLDN1 gene expression." (PMID 28659146, 2017). "The expression of Claudin-1 varies among tumor tissues—high levels have been observed in lung squamous cell, colon and liver carcinoma, and low levels in breast carcinoma." (PMID 28126724, 2017). "Then, CLDN1 gene expression was evaluated in 143 primary tumor samples that were classified in the different molecular subtypes." (PMID 28659146, 2017). "Aberrant CLDN1 expression in tumor cells can lead to alteration of the tight junction structure and function, or dysregulation of cell signaling pathways." (PMID 28659146, 2017). "Lastly, WB showed that Claudin 1, Claudin 4, and Claudin 7 were closely related to tumour growth and metastasis." (PMID 28376864, 2017). "The strong association between expression of CLDN1 gene, methylation of GFRA3 promoter and expression of IL-8 gene in tumor tissue warrants further investigation in regards to the influence of H. pylori infection, but this is beyond the scope of this study." (PMID 26984265, 2016). "In the present study, we investigated the biological relationship between Nm23H1 and CLDN1, and clarified their roles in tumor invasion of ESCC cells." (PMID 27376780, 2016). "At the invasive front of the tumor, single cancer cells appeared to lose or reduce their expressions of both Nm23H1 and CLDN1 (arrows)." (PMID 27376780, 2016). "Claudin 1 interaction with the MMPs in the extracellular matrix also demonstrates its involvement in invasion and tumor progression." (PMID 26633531, 2015). "We found that tumor growth was significantly suppressed in CLDN1-KD groups compared with control groups." (PMID 25544763, 2015).
tumor (continued). "Claudin 1 membrane immunoreactivity was observed in 81.1% (77/95) of tumor samples, and the positive cases were 28.6% (22/77)." (PMID 26312763, 2015). "CLDN1 has been shown to function as an oncogene or tumor suppressor depending on the specific cellular context." (PMID 26067567, 2015). "The tight junction protein 1 (claudin-1) is an important inhibition protein of tumor infiltration function." (PMID 24758579, 2014). "Taken together, these results confirm the role of claudin-1 as a promoter of colon tumorigenesis and further identify the role of the dysregulated antigen-tumor interaction and inflammation in claudin-1-dependent upregulation of colon tumorigenesis." (PMID 24997475, 2014). "Combined together, we concluded that claudin-1 expression decreased tumor latency to increase tumor growth in the DSS-APC model of colon tumorigenesis." (PMID 24997475, 2014). "More specifically, we focused on a select number of SATB1 target genes that are known to participate in tumorigenesis and metastasis (e.g. tumor/metastasis suppressors BRMS1, Kiss1, Claudin-1; tumor/metastasis promoters c-Abl, MMP3, ErbB2 and Snail)." (PMID 24260116, 2013). "Both H. pylori-exposed gastric epithelial cells and the tumor biopsies demonstrated significant up-regulation of five common genes (IL-8, CLDN1, KRT17, CLDN7 and MMP7) and down-regulation of four common genes (GPER, KIAA1324, ADA and SLC9A2)." (PMID 24321518, 2013). "In 81% of the positive cases for Cldn-1, there was a downregulation of the protein in the lowermost and in 60% in the uppermost layers of epidermal tumor parts." (PMID 23390516, 2013). "Our sample number is small, and a much larger study would be required to reveal statistically significant correlation between CLDN1 expression and sample subgroups, such as the histological subtypes, different tumor stages and H. pylori status." (PMID 24321518, 2013). "Very high CLDN1 expression in the tumor was identified as an independent and significant predictor gene of reduced post-operative survival." (PMID 24321518, 2013). "In unkeratinized tumor cells, Cldn-1 was heterogeneously expressed, ZO-1 was weak, whereas Ocln and Cldn-4 were absent." (PMID 23390516, 2013). "Claudin-1 significantly increases xenograft tumor growth and metastatic behavior in athymic mice through its effects on E-cadherin expression and β-catenin/Tcf signaling in colon carcinoma." (PMID 24009024, 2013). "This is supported by findings in neoplasia induced by 7,12-dimethylbenz(a)anthracene and 12-O-tetradecanoyl-phorbol-13-acetate treatment of mouse models, which also exhibit downregulation of Cldn-1 in the basal cell layer." (PMID 23390516, 2013). "The goal of this study is to report the expression of Snail-1, E-cadherin and claudin-1 in colonic neoplasia, as colorectal tumors provide an excellent system to study the genetic alterations involved in the development of common human neoplasms." (PMID 22408413, 2012). "The tight junction proteins Claudin 1 and Claudin 7 were stained immunohistochemically in the tumor and in the surrounding normal mucosa." (PMID 23675182, 2010). "In normal, surrounding breast tissue, the mean value of crossing points (cycle threshold) was 34,02 whereas in the tumour tissue samples it was 36,22 (indicating low levels of CLDN1 mRNA)." (PMID 15743508, 2005). "CLDN1 mRNA was downregulated by 12-fold in the sample (tumour) group as compared with the control group using GAPDH as the reference gene." (PMID 15743508, 2005). "CLDN1 was downregulated by 12-fold in the sample (tumour) group in comparison with the control group using GAPDH as the reference gene." (PMID 15743508, 2005). "CLDN1, INHBA, and CXCL12 may serve as clinically relevant biomarkers in CRC, particularly as prognostic indicators linked to tumor progression, immune modulation, and metastatic potential." (PMID 40426863, 2025). "CLDN1 acts as a tumor suppressor and is a direct target of RUNX3." (PMID 40687428, 2025).
tumor (continued). "Additionally, the cancer cells in the invasive front were highly expressed Cldn1 compared with the cells in the center of the tumor." (PMID 40361399, 2025). "Studies indicate that CLDN1 overexpression may enhance tumor cell proliferation and migration, while its downregulation can compromise tight junction integrity and augment cancer cell invasiveness." (PMID 41249135, 2025). "The role of CLDNs in cancer remains unclear; however, recent research suggests that the CLDN1-dependent pathway might play a role in suppressing CRC expression and is associated with tumor invasiveness and prognostic factors." (PMID 40426863, 2025). "To corroborate the in vitro studies, we examined whether CLDN1 inhibitors used alone or in combination with IM exhibited anti-tumor activity against IM-naive and -resistant GIST xenografts." (PMID 40943068, 2025). "Claudin-1 can function as a tumor promoter or suppressor depending on the type of cancer." (PMID 38338705, 2024). "Moreover, exosomal-BKV-B1-miR-3p derived from BK-infected BC cells would be transferred to ECs and increase its adhesion to tumor cells by switching on the CLDN1 enhancer, which subsequently destroyed endothelial monolayers and increased permeability." (PMID 38245774, 2024). "Claudin-1 (CLDN1), a tight junction protein that regulates epithelial cell permeability, is involved in biological processes such as cell adhesion, cell differentiation, and DNA damage repair; it has also been implicated in tumour formation." (PMID 39457456, 2024). "On the contrary, claudin-1/4 upregulation may suppress tumor migration, invasion, and EMT by affecting several signaling pathways." (PMID 39458944, 2024). "Notably, TMX4, ALPL, PTX3, BHLHE40, TNFRSF12A and CST3 demonstrated significant overexpression in LUSC tumour tissues, whereas CLDN1, VKORC1 and ADD3 exhibited significant underexpression." (PMID 38520221, 2024). "Among CLDNs, CLDN1 possesses the ability to promote the invasive capabilities by tumour cells." (PMID 38201579, 2023). "By contrast, a tumor-promoting role of CLDN1 has also been highlighted." (PMID 37318881, 2023). "It has been hypothesized that claudin-1 induces tumor lymphatic vessel generation, thereby enhancing the spread of the tumor." (PMID 37686483, 2023). "Decreased CLDN1 expression may promote the proliferation, invasion, and metastasis of tumour cells, including PC." (PMID 38201579, 2023). "With the establishment that tumor cells circulate in clusters, maintenance of this clustered state by CLDN1-mediated cell adhesion may be key to acquiring the metastatic properties of CRC cells." (PMID 37318881, 2023). "Furthermore, CLDN1 overexpression is correlated with the presence of distant metastases, tumour infiltration, and worse prognosis." (PMID 38201579, 2023). "However, the authors revealed that under-expression of CRIM-1 increases tumor invasion and epithelial-mesenchymal transition by reducing E-cadherin expression and increasing claudin-1 and MMP-2 and -9 expression." (PMID 38188015, 2023). "In the colon, claudin-1 plays a dual role as a tumour-suppressor gene and as an oncogene." (PMID 37102018, 2023). "Normal and tumour tissues from such patients were analysed by qRT-PCR for the following 12 genes; six from RNA-seq: CLDN1, MAGEB2, CD24, CEACAM6, IL1B and ISG15 and six from RNA-seq and proteomics cross-linking: AKR1C3, TNFAIP2, RAB7A, LGALS3BP, PSCA and SSRP1." (PMID 36428603, 2022). "On the other hand, the mRNA levels of CLDN1, which codify Claudin1, which were observed up-regulated in our study upon inhibition of miR-182-5p, have been reported to be upregulated or downregulated in tumor cells." (PMID 35204688, 2022). "CLDN1 is thought to be a tumor suppressor in lung and prostate cancers." (PMID 36620607, 2022).
tumor (continued). "The analysis of the expression of claudins in colon tissue and in IPEC-J2 cells showed changes in the expression of only the sealing TJ proteins: claudins-3 and -4 in the tumor and claudin-1 and -4 in IPEC-J2 cells, while the expression of other TJ proteins did not change." (PMID 34638619, 2021). "Notably, overexpression of miR-29a acted to reduced HCC cell proliferation and migration in vitro and tumor growth in vivo in a CLDN1-dependent manner." (PMID 33803804, 2021). "Most authors point out the connection between the overexpression of claudin-1 and a positive prognosis in the development of cancer, as well as the connection between its decreased level and an increase in the malignancy of neoplasms." (PMID 34638619, 2021). "The role of Claudin 1 and Occludin in tumor progression and metastasis remained controversial." (PMID 33613746, 2021). "However, the molecular mechanisms by which CLDN1 affects tumorigenesis and tumor progression in OC remain largely unstudied." (PMID 33828978, 2021). "Developing strategies to target CLDN1 may lead to enhanced chemosensitivity and hinder tumor metastasis and OC recurrence." (PMID 33828978, 2021). "In addition, it reduced mesenchymal markers (N-cadherin and snail) and increased epithelial markers (E-cadherin and claudin-1) in A549 cells, suggesting that B5 can reduce tumor migration through modulated mesenchymal–epithelial transition in NSCLC." (PMID 34576028, 2021). "The idea to reduce expression of CLDN1 should also be considered in the context of the use of general DNA hypomethylating agents that are being used to reactivate tumor suppressor and pro-apoptotic genes and potentiate response to other cytotoxic chemotherapeutic agents, including in solid tumors." (PMID 33828978, 2021). "The high expression of claudin-1 was significantly related to the better tumor type (n = 6; RR, 0.60; 95% CI, 0.49–0.73; P < 0.00001), negative venous invasion (n = 4; RR, 0.81; 95% CI, 0.70–0.95; P = 0.001), and negative lymphatic invasion (n = 4; RR, 0.83; 95% CI, 0.74–0.92; P = 0.0009)." (PMID 32855635, 2020). "In addition, claudin-1 was related to the better tumor type and the less venous invasion and lymphatic invasion." (PMID 32855635, 2020). "This meta-analysis assessed the association between claudin-1 and prognosis, and the results showed that the high-expressed claudin-1 is correlated with lower aggressive tumor behavior and better prognosis (OS: HR, 0.46; 95% CI, 0.28–0.76; P = 0.002; DFS: HR, 0.44; 95% CI, 0.29–0.65; P < 0.0001)." (PMID 32855635, 2020). "The over expression of claudin 1 and 3 in these triple negative tumours may be worth considering as possible therapeutic targets." (PMID 31044387, 2020). "This led to the suggestion that claudin 1 may be used as a therapeutic target for tumours over-expressing it." (PMID 31044387, 2020). "A lot of studies have reported that the expression of claudin-1 correlates with tumor invasion: it is said that claudin-1 may improve anti-apoptosis ability and stimulate metastasis." (PMID 32197343, 2020). "However, current studies indicate that some members of the claudin family, such as CLDN4 and CLDN1, play an oncogenic role in some types of tumours." (PMID 32093760, 2020). "We also used TCGA data to compare CLDN-1 expression in normal and tumor tissues." (PMID 31952355, 2020). "CLDN-1 acts as a tumor suppressor in ER+ and as a tumor promoter in ER- cancer subtypes." (PMID 31952355, 2020). "So, we assume that polymorphisms in CLDN1 might influence the expression level of CLDN1 protein and then influence the tumor differentiation." (PMID 30910845, 2019). "Additionally, miR-146b, miR-204, miR-7-2, and FN1 were associated with the tumor stage of PTC, and TNFRSF12A and CLDN1 were related to the prognosis of PTC." (PMID 30414611, 2018).